CCL19 (C-C motif chemokine ligand 19)
Diseases named in the same sentence as CCL19 in open-access papers (continued):
Sharing a sentence is not in itself a finding about the gene and the disease.
viral infection (22 papers, 2010 to 2025). "Hence, we systematically evaluated the contributions of CCL19 and CCR7 expression polymorphisms, signal transduction and CCL19-based adjuvant mechanisms in viral infections." (PMID 31632965, 2019). "CCL19 is a chemokine that is commonly upregulated as a result of viral infections, and attracts dendritic cells and T lymphocytes." (PMID 36825211, 2022). "Suppression of the CCR7 and CCL19/CCL21 axis results in dysfunction of T-cells during viral infection." (PMID 32731586, 2020). "CCL19 is involved in T-cell recruitment during viral infection, and binds to the CCR7 receptor which is expressed on immune cells and cancer cells." (PMID 33013908, 2020). "Suppression of the CCL19 axis results in T-cell dysfunction during viral infection." (PMID 38397195, 2024). "CCL19 could act as a lymphocyte chemoattractant factor via CCR7 in some virus infections or inflammatory disorders." (PMID 33668643, 2021). "In short, the role of CCL19 in chickens is summarized as follows: on the one hand, the main role of CCL19 is to recruit immune cells into the lesions to limit virus infection and inflammatory responses; on the other hand, CCL19 could facilitate virus invasion." (PMID 33668643, 2021). "CCL19 is a pro-inflammatory cytokine that has been linked with persistent viral replication and inflammation such as in the context of HIV-1 infection, underlining that persistent SARS-CoV-2 infection in BLT-L mice recapitulate key immunological features of chronic viral infection." (PMID 40920821, 2025). "These aged FRCs formed disrupted reticular cell networks and produced less T cell chemokines CCL19 and CCL21 following viral infection." (PMID 36802099, 2023). "While the increase of Cxcl9+ FRCs upon viral infection is well documented, it remains unclear if Cxcl9+ FRCs represent a unique subset that is rapidly expanded upon infection or a transient state which Ccl19+ FRCs can enter during inflammatory immune responses." (PMID 36433946, 2022). "Chemokine CCL19, together with its receptor CCR7, is one of the most important factors recruiting immune cells into target organ during virus infection." (PMID 35935208, 2022). "We present and discuss the expression, signaling adaptor proteins and effects of CCL19 and CCR7 as these molecules differentially impact different viral infections and viral life cycles in host homeostatic strategies." (PMID 31632965, 2019). "CXCL13, CCL19 and CCL21 have previously been shown to be essential components of the local airway immune response to viral infection and to be involved in iBALT formation, a recognised feature of long term pathogen exposure." (PMID 24847941, 2014). "The inefficient chemokine receptor modulation of DCs by viral infection results in poor migration toward the CCR7 ligand, CCL19." (PMID 23301113, 2013). "In contrast, targeting LTβR in CCL19-expressing cells (CCL19-Cre) did not affect LN development and structure, but impaired resistance to viral infection." (PMID 34335629, 2021). "In this review, we evaluate the functional efficacies of CCL19 and CCR7 in viral infection and prevention, which may facilitate the development of more potent, durable and safe T cell-based anti-virus pharmaceuticals or vaccines." (PMID 31632965, 2019). "Expression of CCL19 and its receptor CCR7 during viral infections." (PMID 31632965, 2019). "In order to evaluate whether the induced adhesion of HCMV-positive mDCs accounts for the reduced CCL19 transwell migration, we performed a transwell migration assay with Mg/EGTA-treated mock cells to induce adhesion in the absence of viral infection." (PMID 28484459, 2017).
psoriasis (20 papers, 2012 to 2025). An autoimmune condition characterized by red, well-delineated plaques with silvery scales that are usually on the extensor surfaces and scalp. "Chemokines encoded by CCR7, CCL2, CCL19, CXCL8, CXCL1, and CXCL2 genes have been identified as potential biomarkers of psoriasis." (PMID 40906403, 2025). "The heatmaps revealed an increase in several classic proinflammatory cytokines such as Tnf, Il6, Il1a, Il23α and a small number of chemokines, including Ccl19, Ccl20, Cxcl13, and Cxcl5, which are typically elevated in psoriasis patients, in CD169+ macrophages." (PMID 38891893, 2024). "The growing understanding of MDSCs in psoriasis pathogenesis, particularly their interaction with chemokines like CCL19, unveils promising new therapeutic possibilities." (PMID 38829444, 2024). "DCs and T cells utilize the CCR7/CCL19 axis as a conduit in influencing the pathogenesis of psoriasis via interactions within psoriatic dermal aggregates." (PMID 38596682, 2024). "This scenario underscores the very important role of CCR7 and CCL19 in the disease progression of psoriasis." (PMID 34361107, 2021). "Stimulation with both TNF-α and IL-1β induced migration to CCL19 in both healthy individuals and patients with psoriasis (P < 0.05), with the effect being more pronounced in IL-1β-stimulated samples." (PMID 21933242, 2012). "Interestingly, the CCL19/CCL21-CCR7 axis is involved in the pathogenesis of diseases such as psoriasis and multiple sclerosis, as well as in tertiary lymphoid structures." (PMID 40455785, 2025). "Fibroblasts produced a number of chemokines (CCL13, CCL19, CCL2, CCL8, CXCL1, CXCL12, CXCL2, CXCL3) that linked to receptors expressed by myeloid cells and T cells, suggesting an important role for fibroblasts in recruiting immune cells in psoriasis." (PMID 37308489, 2023). "In addition, the SFRP2+ inflammatory fibroblasts in psoriasis share with the COL6A5+COL18A1+ fibroblasts in atopic dermatitis the expression of CCL19 which is capable of recruiting CCR7+LAMP3+ cDC2A61." (PMID 37308489, 2023). "Rittié and Elder have identified CCL19 and CCR7 as potential mediators of immune organization in psoriasis." (PMID 38829444, 2024). "The heatmap showed that C–C motif chemokine ligands (Ccl3, Ccl4, Ccl5, Ccl17, Ccl19-Ps2, and Ccl22) were expressed at higher levels in IMQ-induced psoriasis." (PMID 38566145, 2024). "Our study highlighted CCR7, CCL2, CCL19, CXCL8, CXCL1, and CXCL2 as potential inflammatory biomarkers in psoriasis, illuminating their molecular mechanisms." (PMID 38829444, 2024). "In conclusion, our study highlights six chemokine genes (CCR7, CCL2, CCL19, CXCL8, CXCL1, and CXCL2) as potential biomarkers in psoriasis, providing insights into the immune and inflammatory responses as pivotal instances in disease pathogenesis." (PMID 38829444, 2024). "The study highlights six chemokine genes (CCR7, CCL2, CCL19, CXCL8, CXCL1, and CXCL2) as potential biomarkers in psoriasis, which are significantly involved in immune and inflammatory responses." (PMID 38829444, 2024). "Previous research has demonstrated that CCL19 and its receptor CCR7, which are expressed by central memory/naive T cells and maturing DCs, exhibit elevated expression in the dermal aggregates of psoriasis lesions." (PMID 38829444, 2024). "This is consistent with previous studies which identified increased CCL19 and CCR7 expression in dermal aggregates in psoriasis skin lesions." (PMID 37131254, 2023). "For example, intrinsic AD in contrast to extrinsic AD showed upregulation of psoriasis-typical genes (e.g., IL22, IL36G, CCL19, and CCL22) complicating discrimination of intrinsic AD and psoriasis." (PMID 31973112, 2020). "The appearance of CXCL12, CCL19, and ANGPTL4 in both directions indicates the positive feedback signaling between keratinocytes and myeloid cells, which likely amplifies the pathogenesis of the psoriasis." (PMID 39999288, 2025).
psoriasis (continued). "This situation highlights the crucial role of CCL19 and CCR7 in the progression of psoriasis." (PMID 38829444, 2024). "Besides, IRF4+ cDC2 cluster that displays an elevated expression of CCL17, CCL22, and a population of fibroblasts that expressed CCL19 and BAFF were reported in psoriasis biopsies." (PMID 34777377, 2021). "In addition, iSALT participates in the pathology of psoriasis, where CCR7 and CCL19 play important roles in the sustainment of these structures (see the section on psoriasis)." (PMID 34361107, 2021). "Similar to the CCL19/CCL21/CCR7 axis, the CCL20/CCR6 axis serves an essential role in the recruitment of inflammatory cells in the immune response and may contribute to a variety of autoimmune diseases, such as MS, IBD, psoriasis, and RA." (PMID 35702353, 2022).
colorectal cancer (18 papers, 2016 to 2025). A primary or metastatic malignant neoplasm that affects the colon or rectum. "Besides, overexpression of CCL19 was discovered to be implicated in tumor progression in cervical cancer, but might be contribute to anti-vascular treatment in colorectal cancer through inhibiting angiogenesis." (PMID 33993869, 2021). "For example, fibroblasts producing CCL19 have been shown to promote the formation of tertiary lymphoid structures, thereby enhancing the anti-tumor IgG response in colorectal cancer liver metastasis." (PMID 40340806, 2025). "In colorectal cancer cells, CCL19 activates CCR7, thereby inducing miR-206 upregulation, which suppresses angiogenesis to inhibit the ERK/MAPK-HIF-1-VEGF pathway." (PMID 38552222, 2024). "Previous study showed that CCl19 suppressed angiogenesis through promoting miRNA-206 in colorectal cancer." (PMID 37212877, 2023). "Meanwhile, the chemokines CCL19 and CXCL13 exhibit a rapid decline in cancer tissues, probably related to CCL19 anti-angiogenic function in colorectum cancer." (PMID 38068961, 2023). "Our previous studies showed that CCL19 suppressed tumorigenesis and metastasis, and the expression of CCL19 was related to the prognosis of patients with colorectal cancer." (PMID 27356745, 2016). "CCL19 was confirmed as a tumor suppressor in colorectal cancer and gastric cancer, while it could enhance the malignancy of small-cell LC." (PMID 38672263, 2024). "Moreover, expression of the other CCR7 ligand, CCL19, is also attenuated in colorectal tissue compared to normal tissue; indeed, colorectal cancer patients with elevated CCL19 had statistically increased survival compared to CCL19-negative patients." (PMID 35203305, 2022). "Chemokine CCL19 inhibits colorectal cancer (CRC) angiogenesis in a CCR7-dependent manner." (PMID 31143705, 2019). "In this study, we detected the influence of CCL19 on colorectal cancer (CRC) angiogenesis." (PMID 30250188, 2018).
gastric cancer (18 papers, 2012 to 2025). A primary or metastatic malignant neoplasm involving the stomach. "On one hand, studies have documented downregulated CCL19 expression in patients with colorectal and gastric cancers, with high CCL19 levels effectively inhibiting proliferation and migration of these cancer cells." (PMID 38300311, 2024). "In database analyses of chemokines in gastric cancer samples, the expression of CCL19 and CCR7 was significantly higher in gastric cancer samples compared with normal tissues." (PMID 39840050, 2024). "Patients with high expression levels exhibited poorer OS, suggesting that CCL19/CCR7 can serve as indicators of poor prognosis in patients with gastric cancer." (PMID 39840050, 2024). "The results also showed that patients with high CCL19 and CCR7 expression had worse overall survival, suggesting that CCL19/CCR7 indicates poor prognosis in gastric cancer." (PMID 37208608, 2023). "Our research came to a similar conclusion that CCL19/CCR7 indicated poor prognosis in gastric cancer." (PMID 37208608, 2023). "Survival analysis of gastric cancer patients in TCGA database demonstrated that the patients with high CCL19 expression had worse overall survival than those with low CCL19 expression, suggesting that CCL19 indicates poor prognosis in gastric cancer." (PMID 37208608, 2023). "Elevated expression of CCR7 or its ligand CCL19 in colorectal or gastric cancer correlated with lymph node metastases, and an improvement in overall survival." (PMID 35203305, 2022). "In this pathway, we have also found a downregulation of CCL19, a tumor suppressor that reduces proliferation, migration and invasion in gastric cancer, and NR0B2, whose downregulation in renal carcinoma is associated with development and progression of cancer." (PMID 34012923, 2021). "The proliferation, migration, and invasion of stomach cancer cells are inhibited by CCL19 via the CCL19/CCR7/AIM2 pathway." (PMID 34367971, 2021). "CCL19 overexpression significantly inhibited gastric cancer cell proliferation and tumor growth through CCL19/CCR7/AIM2 pathway." (PMID 34544443, 2021). "We compared CCL19/CCR7 expression in gastric cancer patients in TCGA database." (PMID 37208608, 2023). "For example, CCL19 inhibited cell proliferation, migration, and invasion in gastric cancer by activating the CCR7/AIM2 signaling pathway, which could be a potential therapeutic approach." (PMID 33344235, 2020). "Regarding the mechanism of FMNP-labeled MSCs recognizing in vivo gastric cancer cells, we consider that CCL19/CCR7 and CXCL12/CXCR4 axis loops may be involved in this course." (PMID 22709686, 2012). "For instance, 19 x 15 CARs (TRUCKs additionally equipped with CCL19) showed a higher cytotoxicity towards investigated gastric cancer (GC) lines in a zebrafish model, reduced expression of T-cell exhaustion markers, as well as better chemotaxis." (PMID 39711794, 2024). "CCL19/CCR7 may be a potential novel therapeutic target in gastric cancer." (PMID 37208608, 2023). "Both CCL19 and CCR7 expression were significantly upregulated in gastric cancer samples compared with that in matched normal samples." (PMID 37208608, 2023). "CCL19 and CCL21 are chemokines and CCR7 is their receptor in gastric cancer and esophageal squamous cell carcinoma." (PMID 36263088, 2022). "In a mouse model of spontaneously developing gastric cancer by activated STAT3 signaling, chemokines CXCL13, CCL19, and CCL21 were induced simultaneously with tumorigenesis and TLS formation." (PMID 35552285, 2022). "Both CCL19 and CCR7 expression were significantly upregulated in gastric cancer tissues." (PMID 37208608, 2023). "Survival analysis demonstrated that both CCL19 and CCR7 indicate poor prognosis in gastric cancer." (PMID 37208608, 2023). "We next detected CCL19 and FOXP3 in gastric cancer tissues by immunofluorescence staining." (PMID 37208608, 2023).
gastric cancer (continued). "Then we analysed CCR7, the receptor of chemokine CCL19, in 32 pairs of cancerous and noncancerous tissues from gastric cancer patients in TCGA database." (PMID 37208608, 2023). "We conducted survival analysis of CCL19 and CCR7 in gastric cancer database." (PMID 37208608, 2023). "Comparing gene expression in 32 pairs of cancerous and noncancerous tissues from gastric cancer patients in TCGA database showed that CCL19 expression was significantly upregulated in gastric cancer samples compared with that in matched normal samples." (PMID 37208608, 2023). "In addition, CCR7/Snail upregulation led to increased levels of the EMT markers, p-ERK, p-AKT and MMP-9 and sped up the G1/S phases of the cell cycle when the human gastric cancer cell line, MGC803, was incubated with CCL19." (PMID 35203305, 2022). "Therefore, CCL19 can activate the CCR7/AIM2 signaling pathway, suggesting that it could be a potential therapeutic method to treating gastric cancer." (PMID 36248785, 2022). "Therefore, both CCL19 and CCR7 may be the potential novel therapeutic targets in gastric cancer." (PMID 37208608, 2023).
lymphoma (18 papers, 2014 to 2025). A malignant (clonal) proliferation of B- lymphocytes or T- lymphocytes which involves the lymph nodes, bone marrow and/or extranodal sites. "For CCR7-dependent B-ALL, CNS entry was linked to ZAP70 activation whereas, for primary central nervous system lymphoma, astrocyte-derived CCL19 retained CCR7-expressing lymphoma cells in the CNS, leading to gliosis and increased risk of gliosis-induced primary central nervous system lymphoma." (PMID 35203305, 2022). "Upregulated expression of CCR4 for CCL5, CCR6 for CCL18, and CCR7 for CCL19 was observed in lymph nodes, where lymphocytes were replaced by lymphoma cells." (PMID 39894788, 2025). "The expression of CCL5, CCL18, and CCL19 was further upregulated in WDL with prominent lymphoma cell infiltration compared with that with scant lymphoma cell infiltration." (PMID 39894788, 2025). "The expression of chemokine receptors, CCR4 for CCL5, CCR6 for CCL18, and CCR7 for CCL19, was upregulated in lymph nodes with conspicuous lymphoma infiltration, likely representing their expression in lymphoma cells." (PMID 39894788, 2025). "Moderate CCL19 expression was detectable on the vast majority of the lymphoma cells in both of the DLBCL subtypes, whereas CCL21 protein expression was found in less than half of the analyzed samples (18 of 43)." (PMID 35887224, 2022). "Deleting CCL19 in mice or CCR7 in lymphoma cells was sufficient to prevent central nervous system lymphoma development." (PMID 35203305, 2022). "Conceivably, the reduced abundance of CCL19/CCL21 in LN of FL is lymphoma instructed and contributes to evasion from anti-tumor immunity." (PMID 34778050, 2021). "Greater than 95% expression was achieved and engineered cells showed substantial migration to chemokine, C-C motif chemokine ligand 19 (CCL19), as well as greater cytotoxicity against antibody-coated lymphoma cells." (PMID 34134774, 2021). "In agreement, a recent study addressing the role of gliosis in lymphoma cell retention in the CNS found that astrocyte-derived CCL19 was required for gliosis-promoted CNSL via enhancing parenchymal retention of lymphoma cells." (PMID 34778050, 2021). "Oncomine dataset analysis indicated that mRNA of CCL19 was ≥ 84.549 and ≥ 1.438 fold elevated in FL samples compared to normal tissue in Compagno lymphoma dataset and Brune lymphoma dataset, respectively." (PMID 34544443, 2021). "CCL19 enhances parenchymal central nervous system (CNS) retention of lymphoma cells (LCs), thereby promoting central nervous system lymphoma (CNSL) formation." (PMID 33228590, 2020). "It appears that the result of Ccr7/9 activation in Runx2/MYC lymphomas is likely to be paracrine growth stimulation, as expression of the cognate ligands (Ccl19, 21, 25) is restricted to thymic stromal cells." (PMID 24586197, 2014). "Inhibition of LTβR signaling by anti- LTβR antibody or knockdown of LTα impaired cell interaction between lymphoma cell and stromal cell, potentially by disrupting production of CCL19 and CCL21 by stromal cells which are ligands for CCR7." (PMID 25211095, 2014). "RNA sequencing revealed upregulated expression of chemokine genes, including CCL5, CCL18, and CCL19, in WDL and that of the corresponding chemokine receptor genes CCR4, CCR6, and CCR7 in the lymphoma cells." (PMID 39894788, 2025). "Our immunohistochemical analysis of the CCL19 and CCL21-ligands of CCR7 demonstrated that the lymphoma cells expressed CCL19, but that CCL21 expression was low in the malignant cells." (PMID 35887224, 2022). "Two-photon microscopy in mice divulged that lymphoma cells transiently enter the brain parenchyma along a CXCL12 gradient; however, cell retention was enhanced by astrocyte-derived CCL19 stimulating central nervous system lymphoma genesis." (PMID 35203305, 2022). "Among them, over-expressed CCL18, CCL19, CXCL9, CXCL10, and CXCL13 were listed in the top 20 deregulated genes in all lymphoma datasets." (PMID 35452413, 2022).